A1CF (APOBEC1 complementation factor)
Description:
Essential component of the apolipoprotein B mRNA editing enzyme complex which is responsible for the postranscriptional editing of a CAA codon for Gln to a UAA codon for stop in APOB mRNA. Binds to APOB mRNA and is probably responsible for docking the catalytic subunit, APOBEC1, to the mRNA to allow it to deaminate its target cytosine. The complex also protects the edited APOB mRNA from nonsense-mediated decay.
Synonyms: ACF; ASP; ACF64; ACF65; APOBEC1CF
Tractability: PROTAC: its protein half-life has been measured.
Gene: Protein-coding gene on chromosome 10 (50,799,409 to 50,885,716, reverse strand). Ensembl gene ENSG00000148584.
Subcellular location: Nucleus; Endoplasmic reticulum; Cytoplasm
Subcellular location (Human Protein Atlas): Nucleoplasm
Pathways (Reactome):
Metabolism of RNA: Formation of the Editosome; mRNA Editing: C to U Conversion
Gene Ontology:
Molecular function: double-stranded RNA binding; enzyme-substrate adaptor activity; protein binding; single-stranded RNA binding; mRNA binding; nucleic acid binding; RNA binding
Biological process: cytidine to uridine editing; mRNA modification; negative regulation of nuclear-transcribed mRNA catabolic process, nonsense-mediated decay; protein stabilization; chromosomal 5-methylcytosine DNA demethylation pathway; negative regulation of mRNA catabolic process
Cellular component: apolipoprotein B mRNA editing enzyme complex; cytoplasm; nucleoplasm; nucleus; mRNA editing complex; endoplasmic reticulum
Genetic constraint (gnomAD): Loss-of-function variants: 45 observed, 69.96 expected, observed/expected ratio (o/e) 0.64, 90% interval 0.51 to 0.82. The upper end of that interval is the gene's LOEUF score, 0.82, which puts it in group 3 of 6, group 1 being the genes least tolerant of losing a copy. Missense variants: 653 observed, 745.51 expected, observed/expected ratio (o/e) 0.88, 90% interval 0.82 to 0.93. Synonymous variants: 272 observed, 272.54 expected, observed/expected ratio (o/e) 1, 90% interval 0.9 to 1.1.
Homologues: Orthologues: chimpanzee A1CF (99% identical), pig A1CF (96% identical), guinea pig A1CF (96% identical), rabbit A1CF (95% identical), dog A1CF (94% identical), macaque A1CF (93% identical), mouse A1cf (92% identical), rat A1cf (92% identical), tropical clawed frog a1cf (82% identical), zebrafish a1cf (80% identical). Paralogues in human: RBM47 (50% identical), RBM46 (47% identical), DND1 (20% identical), HNRNPA3 (15% identical), HNRNPA2B1 (14% identical), RBM19 (14% identical), RBMX (14% identical), HNRNPA1 (13% identical), RBMXL1 (13% identical), RBM4 (13% identical), HNRNPA1L3 (13% identical), HNRNPA1L2 (13% identical), and 24 more.
Diseases named in the same sentence as A1CF in open-access papers:
A1CF is named in the same sentence as 25 diseases in open-access papers, as found by Europe PMC text mining. Sharing a sentence is not in itself a finding about the gene and the disease. The quoted sentences say what the papers report.
gout (6 papers, 2014 to 2022). A condition characterized by painful swelling of the joints, which is caused by deposition of urate crystals. "Meta-analysis also revealed a significant association with gout in both SNPs (Pmeta = 3.16 × 10–4, OR with 95% CI: 1.39 [1.17–1.66] for rs10821905 of A1CF, Pmeta = 7.28 × 10–5, OR with 95% CI 1.32 [1.15–1.51] for rs1178977 of BAZ1B)." (PMID 33517564, 2021). "Replication studies revealed both SNPs to be significantly associated with gout (P = 0.0366, odds ratio [OR] with 95% confidence interval [CI]: 1.30 [1.02–1.68] for rs10821905 of A1CF, P = 6.49 × 10–3, OR with 95% CI: 1.29 [1.07–1.55] for rs1178977 of BAZ1B)." (PMID 33517564, 2021). "In the absence of alcohol exposure, genetic variants in the GCKR and A1CF genes have a stronger role in determining the risk of gout." (PMID 28679452, 2017). "Interaction of any alcohol exposure with GCKR (rs780094) and A1CF (rs10821905) influenced the risk of gout in Europeans (interaction term 0.28, P = 1.5 × 10−4; interaction term 0.29, P = 1.4 × 10−4, respectively)." (PMID 28679452, 2017). "Rather, the loci (GCKR and A1CF) interacting with alcohol consumption in determining the risk of gout in Europeans are involved in glycolysis and apolipoprotein metabolism, respectively." (PMID 28679452, 2017). "In the absence of alcohol exposure, genetic variants in the GCKR and A1CF genes have a stronger role in gout." (PMID 28679452, 2017). "For example, there are loci associated with control of serum urate levels that contain genes that are also associated with serum Tg levels (GCKR, MLXIPL, A1CF) and gout." (PMID 25432151, 2014). "Interestingly, there is association between urate levels and risk of gout of the gene (A1CF), which encodes the complementation factor for the APOBEC enzyme that edits apo B mRNA." (PMID 25432151, 2014). "This study shows the first known association between SNPs of A1CF, BAZ1B and clinically-defined gout cases in Japanese." (PMID 33517564, 2021). "This prompted us to examine the association between common variants of A1CF, BAZ1B and gout using clinically-defined Japanese gout patients through a candidate gene approach, and to meta-analyze it with our previous gout GWAS data." (PMID 33517564, 2021). "The present study showed, for the first time, an association between rs10821905 of A1CF as well as rs1178977 of BAZ1B and gout in a Japanese population." (PMID 33517564, 2021). "Another Chinese study showed that rs10821905 of A1CF gene, rs2941484 of HNF4G gene, and rs4971101 and rs2070803 of TRIM46 gene were associated with susceptibility to gout." (PMID 30123371, 2018). "Six of the genes (A1CF, GCKR, ABCG2, TRIM46, SLC17A1 and HNF4G (novel gout-associated gene)) were still significantly associated with gout in males after multiple correction (all PFDR < 0.05)." (PMID 28252667, 2017). "In addition, A1CF and TRIM46 were identified as associated with gout in the Chinese population for the first time (PFDR < 0.05)." (PMID 28252667, 2017). "Among the fourteen genes, six genes (ABCG2, SLC2A9, TRIM46, SLC17A1, A1CF and SLC17A4) affected both the elevation of the serum urate level and the development of gout from hyperuricemia and were identified as risk factors for gout." (PMID 28252667, 2017). "This systematic analysis provides the first evidence for an interaction of alcohol consumption (an established dietary risk factor for gout) with previously identified urate/gout-associated loci GCKR and A1CF that are predominantly involved in glycolysis and lipid homeostasis." (PMID 28679452, 2017). "Of these, rs10821905 of A1CF and rs1178977 of BAZ1B showed the greatest and the second greatest significant effect size for increasing SUA level in the Japanese population, but their association with gout is not clear." (PMID 33517564, 2021).
gout (continued). "Six genes (A1CF, ABCG2, SLC2A9, TRIM46, SLC17A1 and SLC17A4) exhibited effects on the development of gout from hyperuricemia in males (all P < 0.05), but none of them exhibited such effects in females (all P > 0.05)." (PMID 28252667, 2017).
glioma (3 papers, 2019 to 2023). A benign or malignant brain and spinal cord tumor that arises from glial cells (astrocytes, oligodendrocytes, ependymal cells). "A1CF, also known as APOBEC1 complementation factor, regulates various cellular processes and exerts a carcinogenic role in renal cell carcinoma, endometrial cancer, and glioma through RNA editing function." (PMID 37120564, 2023). "Their roles in modulating malignant progression of glioma and the cross-talk between A1CF, FAM224A, miR-590-3p and ZNF143 were elucidated." (PMID 31186064, 2019). "Knockdown of A1CF significantly suppressed the biological behaviors of glioma cells via destabilizing FAM224A." (PMID 31186064, 2019). "In our study, we discovered that overexpression of A1CF remarkably upregulated FAM224A expression in glioma cells." (PMID 31186064, 2019). "LncRNAs microarray analysis revealed that FAM224A was remarkably downregulated in glioma cells following knockdown of A1CF, implying that FAM224A may participate in A1CF-induced modulation on glioma cells." (PMID 31186064, 2019). "Our present data revealed that A1CF and FAM224A were obviously upregulated in glioma tissues and cells." (PMID 31186064, 2019). "In this study, we confirmed that A1CF and FAM224A were overexpressed in glioma tissues and cell lines." (PMID 31186064, 2019). "The Cell Counting Kit-8 assay, migration and invasion assays, and flow cytometry analysis were conducted to evaluate the function of A1CF, FAM224A, miR-590-3p, ZNF143 and ASAP3 in the malignant biological behaviors of glioma cells." (PMID 31186064, 2019). "In the present study, the endogenous expression of A1CF, FAM224A, miR-590-3p and ZNF143 were investigated in glioma tissues and cell lines." (PMID 31186064, 2019). "A1CF was upregulated and functioned as an oncogene via stabilizing and increasing FAM224A expression; moreover, high A1CF and FAM224A expression levels indicated a poorer prognosis for glioma patients." (PMID 31186064, 2019). "Additionally, inhibition of A1CF and FAM224A obviously reduced ZNF143 expression in glioma cells, and upregulation of ZNF143 reversed the prohibitive effects on glioma cells induced by miR-590-3p overexpression." (PMID 31186064, 2019). "Finally, the xenograft tumor growth assay further ascertained the biological roles of A1CF, FAM224A and miR-590-3p in glioma cells." (PMID 31186064, 2019). "In addition, depletion of A1CF or FAM224A markedly attenuated the proliferation, migration and invasion of glioma cells, whereas promoted cellular apoptosis." (PMID 31186064, 2019). "Knockdown of A1CF or FAM224A obviously inhibited cell proliferation, migration and invasion, while promoted apoptosis in glioma cells when compared with the negative control groups." (PMID 31186064, 2019).
breast carcinoma (2 papers, 2016 to 2019). "Accumulating evidence has highlighted that RNA binding protein APOBEC1 complementation factor (A1CF) is involved in various cellular processes by modulating RNA expression, and acts as an oncogene in breast cancer." (PMID 31186064, 2019). "Recent research showed that A1CF acts as an oncogene in breast cancer by enhancing the stability of Dickkopf1." (PMID 31186064, 2019). "However, before validation of the role of A1CF in breast cancer, more studies are required to address the prevalence of A1CF (-8aa) in breast cancer and whether blocking A1CF (-8aa) or the corresponding alternative splice event can help cancer therapy." (PMID 27231908, 2016). "Given the important role of RBM47 in progression of breast cancer, and similar structure, function between RBM47 and A1CF, we hypothesize that A1CF (-8aa) or A1CF may also play a biological role in breast cancer." (PMID 27231908, 2016). "Moreover, we further validated that A1CF (-8aa) but not A1CF contributed to the proliferation of breast cancer cells, thus again firstly uncovering the biological significance of A1CF (-8aa)." (PMID 27231908, 2016).
germ cell tumor (2 papers, 2020 to 2025). A benign or malignant, gonadal or extragonadal neoplasm that originates from germ cells. "During tumorigenesis, the APOBEC1 complementation factor (A1CF) promotes the development of germ cell tumors." (PMID 41446042, 2025).
hepatocellular carcinoma (2 papers, 2016 to 2023). A malignant tumor that arises from hepatocytes. "Moreover, germ-line deletion of A1CF led to embryonic lethality and knock-down of A1CF caused apotosis in rat hepatoma cells." (PMID 26848653, 2016). "Alternative splicing of KhkC in the liver is mediated by APOBEC1 complementation factor (A1CF), while heterogeneous nuclear ribonucleoprotein H1/2 (hnRNPH1/2) mediates a c-myc-driven switch of KHKC to the KHKA isoform in dedifferentiated hepatocellular carcinoma (HCC) cells." (PMID 37559908, 2023).
renal dysfunction (2 papers, 2021 to 2024). "A variant in A1CF (rs10994860) protected against hyperfiltration and renal dysfunction (beta −0.69852, p = 0.020), whereas a variant in SYPL2 (rs12136063) was associated with an increased risk (beta 0.57907, p = 0.04208)." (PMID 38791464, 2024). "This study has replicated APOL1 gene variants: (G1)-rs73885319 and (G2)-rs71785313, shown to be strongly associated with renal dysfunction in SCD patients, as well as A1CF-rs10994860, SYPL2-rs12136063, WNT7A-rs6795744, and TMEM60-rs6465825 in Cameroonian SCD patients." (PMID 33790942, 2021).
steatosis (2 papers, 2023 to 2024). Increased lipid within the cytoplasm of cells. "Despite the several common phenotypic and biochemical outputs of hepatic TRIM21 overexpression and A1CF silencing, we noticed that the improvement in steatosis was more profound in Ad-Trim21 mice compared with GalNAc-siA1cf–treated mice." (PMID 37937648, 2023). "In this study, we report an upstream mechanism of KHK-C regulation through TRIM21-mediated A1CF ubiquitination and degradation that inhibits KHK-C and establishes a protective mechanism suppressing fructose-induced steatosis." (PMID 37937648, 2023). "Expression profiling in livers of mice with developing steatohepatitis revealed that, at the time when livers start to accumulate lipids and develop steatosis (12 weeks of NASH diet), A1CF and KHK are induced, while TRIM21 expression starts to increase." (PMID 37937648, 2023). "In vivo silencing of A1cf via administration of GalNAc-siRNAs reduced lipogenic gene expression and liver steatosis and phenocopied the effects of pharmacologic inhibition of KHK, making it a candidate therapeutic target for ameliorating steatosis during NASH progression." (PMID 37937648, 2023).
bladder cancer (1 paper, 2023). "Finally, in order to explore the enriched pathways of TPP-related genes and A1CF in bladder cancer cohort, we then performed the GSEA, GSVA and GO enrichment analysis." (PMID 37869074, 2023).
Hepatic steatosis (1 paper, 2023). Steatosis is a term used to denote lipid accumulation within hepatocytes. "Given that A1CF-mediated KHK-C expression promotes fructose metabolism and, ultimately, hepatic steatosis at early stages of NASH development, we also investigated A1CF’s role as a contributor to NASH progression." (PMID 37937648, 2023).
renal carcinoma (1 paper, 2024). A carcinoma arising from the epithelium of the renal parenchyma or the renal pelvis. "The results of anchorage-independent growth and Western blot analysis in renal cancer cells indicated that the A1CF and NKRF interaction modulates anchorage-independent growth through p65 and IFN-β in renal carcinoma cells." (PMID 38612387, 2024). "Our study is the first to demonstrate the signaling pathway regulation and oncogenic characteristics of A1CF in renal carcinoma cells, thus expanding its biological function." (PMID 38612387, 2024). "Based on the literature and our data, we propose a working model of A1CF function in the regulation of NF-κB activity in renal carcinoma cells." (PMID 38612387, 2024). "The results indicated that shRNA#1 exhibited superior silence efficiency, and it was used to screen A1CF-silenced stable cells in renal cancer cells." (PMID 38612387, 2024). "Whole-cell lysates were prepared from stable renal cancer cells with disrupted A1CF expression, and we detected the upstream and downstream regulators of NKRF and NF-κB." (PMID 38612387, 2024). "To determine the function of the A1CF–NKRF interaction in anchorage-independent growth of renal cancer cells, we overexpressed full-length A1CF or RRM deletion mutants separately." (PMID 38612387, 2024). "Here, we determined the role of A1CF in two renal cancer cell lines (OSRC-2 and 786-O)." (PMID 38612387, 2024). "Moreover, we revealed the tumor-promoting effects and NF-κB regulatory function of A1CF in renal carcinoma cells." (PMID 38612387, 2024). "This study is the first to demonstrate the oncogenic characteristics and role of A1CF in addition to RNA editing in renal carcinoma cells and may provide additional therapeutic targets for RCC." (PMID 38612387, 2024). "To determine whether A1CF promotes anchor-independent growth of renal cancer cells, we performed soft agar assays and found that A1CF-overexpressing cells significantly increased the number of colonies compared with that of the control." (PMID 38612387, 2024). "A1CF inhibits p65(p-S536) phosphorylation and IFNβ expression and its accumulation in the nucleus depends on the interaction with NKRF, and the A1CF-NKRF-p65/IFNβ signaling axis is important to renal carcinoma growth." (PMID 38612387, 2024). "Our results indicate an outside role for A1CF in RNA editing, protein binding independent of RNA or DNA in NF-κB signal pathway regulation, and promoting tumor characteristics in renal carcinoma cells." (PMID 38612387, 2024). "The A1CF RRM deletion mutants, particularly A1CF ∆RRM1, nearly rescued the reduction in p65(Ser536) phosphorylation and IFN-β expression and abolished A1CF-promoted renal cancer cell proliferation as measured by the EdU and MTT assays." (PMID 38612387, 2024).
cancer (4 papers, 2016 to 2023). A tumor composed of atypical neoplastic, often pleomorphic cells that invade other tissues. "We apply easyCLIP to the 33 most recurrent cancer mutations across 28 RBPs, finding increased RNA binding per RBP molecule for KHDRBS2 R168C, A1CF E34K and PCBP1 L100P/Q cancer mutations." (PMID 33692367, 2021). "In three cases, recurrent cancer-associated missense mutations in RBPs increased binding to RNA: KHDRBS2, A1CF, and PCBP1." (PMID 33692367, 2021). "Inhibition of A1CF dampens the malignant behaviors of cancer cell." (PMID 37120564, 2023).
tumor (3 papers, 2018 to 2024). "Our findings demonstrate the tumor-promoting role of A1CF through the downregulation of p65 phosphorylation at Ser536 and competitive binding to the p65 interaction site on NKRF in kidney-derived cells." (PMID 38612387, 2024). "FCM data indicated that overexpression of A1CF decreased apoptosis, whereas A1CF knockdown increased apoptosis of OSRC-2 and 786-O cells, which is consistent with the reported results in other tumor cells or kidney epithelial cells." (PMID 38612387, 2024). "Finally, A1CF and FAM224A inhibition combined with overexpression of miR-590-3p predominantly suppressed tumor growth, as well as elongating the survival time of nude mice." (PMID 31186064, 2019). "Additionally, knockdown of A1CF and FAM224A combined with miR-590-3p overexpression resulted in the smallest tumor sizes among all of the groups." (PMID 31186064, 2019). "Collectively, knockdown of A1CF could increase miR-590-3p expression via downregulating FAM224A; however, the molecular mechanisms of miR-590-3p-induced tumor-suppressive functions still remain unknown." (PMID 31186064, 2019).
kidney disease (1 paper, 2016). "Thus, it is intriguing to address the role of A1CF in the occurrence and development of mammalian kidney disease." (PMID 26848653, 2016). "Whether A1CF has a biological function during the occurrence and development of kidney disease has been an open question in view of the finding that A1CF is also abundant in the kidneys." (PMID 26848653, 2016).
metabolic disease (1 paper, 2023). A congenital disorder (due to inherited enzyme abnormality) or acquired (due to failure of a metabolically important organ) disorder resulting from an abnormal metabolic process. "Genetic ablation of A1cf markedly reduced the expression of the KHK-C isoform and protected mice from fructose-induced metabolic disease, thereby phenocopying KHK deficiency." (PMID 37937648, 2023).
A1CF also shares sentences with these, for which no sentence is quoted: atherosclerosis (1 paper); atransferrinemia (1); Atrophy (1); clear cell renal cell carcinoma (1); colitis (1); cryptorchidism (1); endometrial cancer (1); hemochromatosis (1); hyperuricemia (1); renal cell carcinoma (1); testicular diseases (1).